LEP (leptin)
Diseases named in the same sentence as LEP in open-access papers (continued):
Sharing a sentence is not in itself a finding about the gene and the disease.
immune dysfunction (32 papers, 2008 to 2025). "Many of the immune disorders in obese patients have been associated with high production of certain adipokines, particularly leptin." (PMID 35734271, 2022). "Low levels of leptin expression due to congenital deficiency or starvation provokes immune dysfunction, which is reversible with leptin administration." (PMID 33673730, 2021). "Reduce type I IFN response through upregulating SOCS3 and leptin; cause other immune dysfunction associated with T cells and B cells." (PMID 34901094, 2021). "The wide impact of leptin on the immune system indicates the important role of leptin in the pathogenic development of immune diseases." (PMID 33597945, 2020). "High leptin levels are also related with a higher prevalence of other immune diseases, such as SLE, and also with increased susceptibility to the development of osteoarthritis (OA)." (PMID 32824322, 2020). "Apart from its well-known effect as key regulator of metabolism, leptin, a pro-inflammatory cytokine and an activator of the immune system, is implicated in a number of inflammatory and immune disorders." (PMID 29910808, 2018). "Furthermore, surplus VAT is associated with immune dysfunction through the dysregulation of increased leptin and decreased adiponectin levels, the activation of immune cells, and alteration of cell-mediated immune responses." (PMID 38275895, 2024). "This immune dysfunction is supported by an inverse relationship between leptin and adiponectin in autistic children." (PMID 38297246, 2024). "Approximately 3% of obese children exhibit mutations in the leptin (LEP) gene and the leptin receptor (LEPR), which can lead to delayed puberty and immune dysfunction." (PMID 37762850, 2023). "About 3% of obese children have mutations in the leptin (LEP) gene and the leptin receptor (LEPR) and can also present with delayed puberty and immune dysfunction." (PMID 33511092, 2020). "The immune dysfunction is not only a consequence of inadequate diet but also contributes in various mechanisms, including the energy homeostasis, metabolism, the role of leptin and it signals to the hypothalamic-pituitary-adrenal axis and peripheral organs." (PMID 30534129, 2018). "The effects of leptin on immune cell activation have been reported in various immune diseases." (PMID 37488474, 2023). "Leptin participates in the interplay of metabolism, inflammation, and immune system disorders." (PMID 37635936, 2023). "Indeed, most studies of the link between leptin and immune dysfunction were performed in mouse models or on human immune cells ex vivo; various effects on adaptative and innate immune markers and cytokine production were observed." (PMID 35011102, 2022). "The elevated leptin and SOCS3 levels could reduce type I IFN response and cause other immune dysfunction associated with T cells and B cells in people with obesity." (PMID 34901094, 2021). "The low systemic leptin levels in HIV patients due to reduced adiposity might contribute to immunodeficiency." (PMID 32824322, 2020). "Lastly, the fact that the leptin level was associated with the occurrence of HAI in our study (independently of the T-cell profile) does not imply that this effect is independent of any other immune dysfunction; specific functional studies of this topic are warranted." (PMID 35011102, 2022). "The low systemic leptin levels in HIV patients due to reduced adiposity may contribute to immunodeficiency." (PMID 29868503, 2018). "Hence, the nature of the direct link between leptin and immune dysfunction is still not clear." (PMID 35011102, 2022).
inflammation (32 papers, 2012 to 2025). Aberrant reaction of the microcirculation characterized by movement of fluid and leukocytes from the blood into extravascular tissues. "Elevated serum leptin and resistin have also been associated with an increased burden of skin and joint inflammation." (PMID 30635024, 2019). "There is evidence that cells in the lung may also be capable of secreting leptin, although it seems more likely that leptin is found in the lung as a consequence of increased microvascular permeability associated with lung inflammation." (PMID 30814978, 2019). "Liver inflammation and fibrosis were increased in leptin-deficient mice." (PMID 30818874, 2019). "Leptin appears to be central in controlling pulmonary immune homeostasis, in particular in acute lung inflammation, but epithelial‐endothelial crosstalk due to leptin needs to be better understood." (PMID 40635334, 2025). "Collectively, these data implicate that Lck leads to development of leptin-induced renal inflammation during aging." (PMID 31788330, 2019). "Leptin has also been reported to increase leukotriene synthesis by alveolar macrophages, leading to pulmonary inflammation." (PMID 30814978, 2019). "Cumulative evidence highlights leptin’s involvement in the pathogenesis of age-related renal inflammation." (PMID 31788330, 2019). "The levels expression of 21 genes, including ADRA2B, CNR1 and LEP were significantly altered in the gastric tissue of NAFLD patients with hepatic inflammation." (PMID 24716593, 2014). "Leptin warrants also a discussion as this is a metabolic hormone produced by adipose tissue cells and has potential, albeit conflicting, roles in autoimmune inflammation and fibrosis." (PMID 37753072, 2023). "Combined, these data indicate that circulating leptin may play a significant role in the development of eosinophilic inflammation in NPs." (PMID 35046816, 2021). "Oxidative stress is induced by leptin and might well play a role in the pulmonary inflammation." (PMID 32844126, 2020). "Furthermore, Foxo4 only reversed the upregulation of MC5R and Leptin (P<0.05), and the downregulation of Foxo4 and IL-6 by αMSH in mRNA level (P<0.05), suggesting that αMSH may inhibit adipocyte inflammation partly via Foxo4 transcriptional regulation." (PMID 28514752, 2017). "HDM increases airway inflammation and BAL eosinophil and lymphocyte numbers, while leptin decreases BAL lymphocytes." (PMID 35610699, 2022). "Cows with persistent postpartum uterine inflammation had higher serum concentrations of TNF-α, IL-6, leptin, but lower insulin and IGF-1 compared to normal and spontaneously recovered cows and there was a temporal association observed during the study period." (PMID 24209779, 2013).
infectious disease (22 papers, 2008 to 2025). A disorder directly resulting from the presence and activity of a microbial, viral, or parasitic agent in humans. "Like malnourishment, leptin deficiency impairs immune function and increases mortality from infectious disease." (PMID 40393800, 2025). "In humans and rodents, loss or downregulation of leptin impaired T cell proliferation and synthesis of inflammatory cytokines, and increased their susceptibility to infectious diseases." (PMID 37238973, 2023). "Throughout this review, it has been highlighted the essential function of leptin in the immune response, as well as the increased susceptibility toward infectious diseases under leptin deficiency/resistance conditions, that can cause an extensive liver injury." (PMID 33316927, 2020). "Consistently, leptin deficiency impairs immune function, making the hosts more vulnerable to infectious disease." (PMID 19087258, 2008). "Similarly, leptin (or Lepr) deficiency impairs immune responses and increases mortality from infectious diseases, whereas elevated leptin augments autoimmune attack." (PMID 40393800, 2025). "Thus, as leptin deficient patients are considered more susceptible to infectious diseases, more serious consequences after SARS-CoV-2 infection would in theory be expected in them." (PMID 35384599, 2022). "Leptin scarcity or resistance is linked with dysregulation of cytokine secretion leading to autoimmune disorders, inflammatory responses, and increased susceptibility towards infectious diseases." (PMID 34220807, 2021). "Leptin is now known to be a key regulator of the innate and adaptive immune responses, with leptin deficiency or resistance leading to the dysregulation of inflammatory responses and increased susceptibility of infectious disease." (PMID 33498782, 2021). "Since, leptin has been reported to induce pro-inflammatory cytokines & chemokines, neutrophil chemotaxis, NK cell cytotoxicity, and T cell functions, therefore its deficiency leads to an increase in susceptibility to infectious diseases." (PMID 30534129, 2018). "However, chronic inflammation results in lower leptin concentrations, probably affecting appetite and food intake control while increasing susceptibility to infectious diseases." (PMID 24603645, 2014). "Thus, leptin deficient patients are more susceptible to infectious diseases." (PMID 34130736, 2021). "A significant progress has been made in understanding the role of leptin in the immune response and in inflammatory and infectious diseases." (PMID 33907162, 2021). "Many studies have been conducted in recent past to understand the role of leptin in immune modulation such as activation of phagocytosis, cytokine polarization and cell-mediated immunity in infectious diseases." (PMID 30534129, 2018). "The distinctive immune responses in various infectious diseases upon leptin treatment were summarized." (PMID 30534129, 2018). "More importantly the mechanism of leptin signaling in various infectious diseases is depends on SOCS3 expression as describes in NF-κB dependent pathway." (PMID 30534129, 2018). "Over the past decade, the role leptin in infectious diseases was extensively explored." (PMID 30534129, 2018). "Hence, it is possible to speculate that leptin might act in the brain to directly regulate metabolic response along with peripheral immune function thereby contributing to better outcomes in various infectious diseases compared with states of relative or total leptin deficiency." (PMID 30534129, 2018). "Therefore, from here onwards, the review focuses on the role of leptin in various infectious diseases." (PMID 30534129, 2018). "Furthermore, there has been increasing evidence that leptin is involved in the pathogenesis of various infectious diseases." (PMID 30534129, 2018). "Therefore, leptin plays an important role in the human immune response to infectious disease." (PMID 24722122, 2014).
infectious disease (continued). "Therefore, taken together these findings reveal that leptin could control the systemic immune defense failure in viral specific immune cells dysfunction and further suggests the possible healing potential for leptin analogs in infectious disease." (PMID 30534129, 2018). "Strikingly, PEM causes a drastic reduction in body fat mass and decreases the circulating concentration of leptin, which, in turn, impairs the generation of proinflammatory mediators [IFN-γ, TNF-α and (NO) nitric oxide], and increases the incidence of infectious diseases." (PMID 30534129, 2018). "Leptin can act as a negative signal for proliferation of T-cells, suppressing the immune system and increasing incidence and severity of infectious disease." (PMID 25090110, 2014).
bacterial infection (18 papers, 2014 to 2024). "Taken together, our results indicate that both the severity of the disease and the type of bacterial infection are associated with elevated leptin levels in CF patients." (PMID 37111072, 2023). "Earlier studies have already described that leptin or leptin receptor deficiency can contribute to an increase in susceptibility to bacterial infections and pneumonia." (PMID 30913261, 2019). "Fourth, leptin (ob/ob) and leptin receptor (db/db) deficient mice showed severe immune abnormalities and greater susceptibility to viral and bacterial infection." (PMID 24722122, 2014). "The diagnostic accuracy of leptin was compared with classic, routinely used markers of inflammation and bacterial infection using ROC curve analyses." (PMID 24669245, 2014). "Additionally, leptin has been used as a mucosal vaccine adjuvant for Rhodococcus equi bacterial infections in mice, and leptin signaling was also associated with higher Helicobacter pylori antibody titers following vaccination." (PMID 25157251, 2014). "Regarding bacterial infection, leptin level was significantly higher in patients infected with P. aeruginosa than in uninfected participants (15.7 ± 7 vs. 9.3 ± 1.7 ng/mL, p = 0.043)." (PMID 37111072, 2023). "The immune system is strongly influenced by leptin’s strong pro-inflammatory effects, and leptin can be secreted by immune stimuli, such as interleukin (IL)-1, IL-6, lipopolysaccharide (LPS), or bacterial infection." (PMID 37691744, 2023). "Mimicking bacterial infection, animal studies identified that LPS induces plasma leptin levels, as well as the adipocyte leptin mRNA expression." (PMID 37238973, 2023). "Leptin treatment also significantly reduced bacterial infection of these epidermal punches by 48 h in culture." (PMID 36093099, 2022). "Down-regulation of leptin/leptin receptor was reported to drastically affect cell resistance to amoeba and bacterial infection in several species." (PMID 34544390, 2021). "In detail, leptin-deficient ob/ob mice revealed an increased susceptibility to Klebsiella pneumoniae and Streptococcus pneumoniae, suggesting that leptin somehow protects against bacterial infection." (PMID 28638490, 2017). "Therefore, the aim of our study was to estimate the impact of the severity of the disease and the type of bacterial infection in CF patients on the serum level of appetite-regulating hormones including leptin, ghrelin, NPY, ASP, POMC, KISS, PYY, and α-MSH." (PMID 37111072, 2023). "Although the patients included in this study were clinically negative for bacterial infection, assessment of leptin levels in serum alone could not be enough to establish their involvement in the disease." (PMID 30913261, 2019). "This suggests that leptin may not to be involved in the acute-phase response to bacterial infection in rats." (PMID 24578293, 2014).
neurological disorders (18 papers, 2007 to 2023). "Due to the many important physiological and developmental functions of leptin, dysregulation in its availability or signaling has been proposed as causal factors for the occurrence of neurological disorders." (PMID 33183317, 2020). "More investigation is required to understand the association between leptin and neurological diseases." (PMID 31130833, 2019). "Understanding leptin-mediated neuroprotective signals and molecular mechanisms underlying remyelination will be helpful to establish therapeutic strategies against neurological diseases." (PMID 31447640, 2019). "Leptin deficiency during development also leads to altered cognitive performance and neurological disorders such as major depressive disorder (MDD), while leptin replacement alleviates these symptoms and improves cognitive development." (PMID 25177272, 2014). "This study uncovers a developmental function of leptin that may be linked to the pathogenesis of neurological disorders and helps understanding how maternal environment can adversely impact offspring brain development." (PMID 30106375, 2018). "The ability of leptin to regulate chloride homeostasis may therefore have important implications not only in health, but also in the emergence of neurological disorders associated with abnormal GABAergic transmission." (PMID 30106375, 2018). "For example, glial leptin can have both beneficial and detrimental effects depending on the cell type and the context of the neurological disease or insult." (PMID 31447640, 2019). "It is known that various endocrine modulators, including leptin and ghrelin, have neuroprotective roles in neurological diseases." (PMID 31447640, 2019). "At the same time, leptin affects neurological diseases during the regulation of metabolic homeostasis." (PMID 31130833, 2019). "Strikingly, leptin levels are also disturbed in several neurological disorders affecting higher brain areas, including MDD." (PMID 25177272, 2014). "Consistently, the reduction of plasma and CSF leptin levels present in HD patients also suggests a disruption of adipose tissue function in this neurological disorder." (PMID 23094041, 2012). "In this study, we investigate the possibility that leptin may regulate the NSCs’ fate decision, which may promote the proliferation and neuronal differentiation of NSCs and thus act positively in neurological disorders." (PMID 37894835, 2023). "Leptin has been shown to be neuroprotective in various neurological disorders." (PMID 37894835, 2023). "It was found that neurological diseases occurred alongside leptin level alterations, suggesting that leptin might be a critical modulator of these diseases, and studying the specific relationship is of significance." (PMID 38098007, 2023). "This study confirms and extends the role of leptin in the ontogenesis of functional GABAergic inhibition and helps understanding how abnormal levels of leptin may contribute to neurological disorders." (PMID 33183317, 2020). "Furthermore, leptin has been shown to have neuroprotective functions in animal models of neurological diseases and demyelination." (PMID 31447640, 2019). "Leptin also shows the protective effects on pediatric neurological diseases." (PMID 31447640, 2019). "It was found that neurological diseases occurred alongside leptin level alterations, indicating that leptin might be a critical modulator of these diseases and studying the specific relationship is of significance." (PMID 31130833, 2019). "These functions suggest that leptin may have protective functions in neurological diseases and insults." (PMID 31447640, 2019). "Thus, there is emerging evidence for the neuroprotective roles of leptin in neurological diseases." (PMID 31447640, 2019). "In conclusion, leptin might be a potential combination therapeutic target but still not sensitive enough to be a biomarker of neurological diseases at present." (PMID 31130833, 2019).
neurological disorders (continued). "Firstly, the control group used was not healthy volunteers but subjects investigated as in-patients for possible neurological disease with negative findings, although, unlikely, this may have influenced serum leptin in controls." (PMID 25505980, 2014). "Thus, despite the fact that leptin has the potential to be a therapeutic drug for neurological diseases through different molecular mechanisms and a target for combination therapy, it is not a clinical biomarker for neurological diseases before a clear mechanism is explored." (PMID 31130833, 2019). "Contrary to the healthy controls with no neurological disease, one study that evaluated serum inflammatory markers revealed significantly increased TNF-α, IL-6, and leptin levels in patients with PPS." (PMID 25886512, 2015).